SRSF2 (serine and arginine rich splicing factor 2)
Diseases named in the same sentence as SRSF2 in open-access papers (continued):
Sharing a sentence is not in itself a finding about the gene and the disease.
myeloid neoplasm (continued). "By contrast, mutations in genes such as SRSF2 and IDH2 afforded similar HRs for different types of myeloid neoplasms." (PMID 37620601, 2023). "Of note, ARCH is characterized by the presence of somatic mutations in genes that are also frequently mutated in SM (e.g., ASXL1, DNMT3A, EZH2, RUNX1, SF3B1, SRSF2 and TET2) and other myeloid neoplasms." (PMID 35626091, 2022). "Aside from DTA mutations, persons with CH also recurrently carried variants in other genes associated with myeloid neoplasms such as JAK2, SRSF2 and SF3B1." (PMID 36131041, 2022). "In particular, the combination of TET2 and SRSF2 mutations is very frequently observed in CMML and highly specific for myeloid neoplasm with monocytosis." (PMID 32674283, 2020). "Mutations in other SF have been found in myeloid malignancies at lower frequencies and with patterns different from those of SF3B1, SRSF2, and U2AF1." (PMID 31766606, 2019). "These were twice combined with additional mutations, including TET2 and SRSF2 mutations in a CMML case, and ASXL1, TET2, and U2AF1 mutations in the disseminated case of an undefined myeloid neoplasm accompanied by HLH (case 10)." (PMID 30084011, 2018). "Furthermore, mutations in SRSF2 and SF3B1, which also contained MGO modifications in this study, are observed in 5–75% of patients with various myeloid neoplasms, particularly chronic myelomonocytic leukemia and refractory anaemia with ring sideroblasts." (PMID 35409048, 2022). "The prognostic impact of U2AF35 mutations is also a controversial issue in myeloid malignancies, while SRSF2 mutations have a negative impact on MDS, MDS/MPN or MPN survival and MDS disease progression." (PMID 23327988, 2012). "In contrast, SRSF2 mutations are not restricted to any specific myeloid neoplasm but are associated with altered myeloid differentiation, disrupting other genes and thereby causing distinctive clinical manifestations of myelofibrosis, monocytosis, and blast phase." (PMID 40562788, 2025). "Around 60% of CD34+ cells from patient 2 [P2(h)] exhibited a heterozygous JAK2V617F mutation (JAK2V617F/WT) whereas no mutation was identified in these cells in ASXL1 and the other genes involved in myeloid malignancies, including TET2, EZH2, DNMT3A, IDH1 and SRSF2." (PMID 24066127, 2013). "Myeloid Malignancy-Related Gene Mutation Screening: A panel of 67 genes associated with the diagnosis, treatment, prognosis, and recurrence of myeloid malignancies (including KIT, SRSF2, TET2, and ASXL2) was analyzed, with no relevant mutations identified." (PMID 40071101, 2025). "For example, microhomology-mediated recurrent deletions of CALR, ASXL1, and SRSF2 and non-recurrent deletions in TET2, DNMT3a, CEBPA, and RUNX1 have been reported in myeloid neoplasms." (PMID 36011278, 2022).
chronic myelomonocytic leukemia (42 papers, 2014 to 2025). A myelodysplastic/myeloproliferative neoplasm which is characterized by persistent monocytosis, absence of a Philadelphia chromosome and BCR/ABL fusion gene, fewer than 20 percent blasts in the bone marrow and blood, myelodysplasia, and absence of PDGFRA or PDGFRB rearrangement. "In this study, we compared findings in SRSF2-mutated patients of the Austrian biodatabase for chronic myelomonocytic leukemia (ABCMML) with the CMML cohort documented in cBioPortal." (PMID 40549056, 2025). "In dieser Studie verglichen wir die Ergebnisse von Patienten mit SRSF2-Mutationen aus der nationalen „Austrian Biodatabase for chronic myelomonocytic leukemia“ (ABCMML) mit jenen von Patienten, die in der internationalen Plattform cBioPortal dokumentiert sind." (PMID 40549056, 2025). "We also identified a significant association between SRSF2 and chronic myelomonocytic leukemia (p = 1.19 × 10−13)." (PMID 35945607, 2022). "About 10% of AML, 20% of MDS, and 50% of patients with chronic myelomonocytic leukemia (CMML) harbor SRSF2 mutations." (PMID 36009519, 2022). "Variants in TET2, JAK2, and SRSF2 occur in 10–60% of patients with sporadic chronic myelomonocytic leukemia." (PMID 35884491, 2022). "Meanwhile, SRSF2 mutations are more common in chronic myelomonocytic leukemia, which alter the RNA-binding characteristics of SRSF2, thereby resulting in extensive changes in splicing patterns and impairment of hematopoietic cell differentiation." (PMID 31065692, 2019). "Mutations in SF3B1, SRSF2, and U2AF1 have been associated with specific disease subtypes with SF3B1 being mostly mutated in MDS-RS, SRSF2 occurring mostly in chronic myelomonocytic leukemia (CMML), and U2AF1 in secondary AML." (PMID 31766606, 2019). "For example, concomitant mutations of TET2 and SRSF2 are very frequent in chronic myelomonocytic leukemia (CMML)." (PMID 27029036, 2016). "Specifically, SRSF2 mutations have been identified as playing a significant role in the pathogenesis of chronic myelomonocytic leukemia (CMML) and MPNs." (PMID 40507313, 2025). "SRSF2 mutations are found in ~50% of chronic myelomonocytic leukemia (CMML), ~20% of MDS, and ~15% of AML patients and ~3–5% of healthy individuals with clonal hematopoiesis (CH)." (PMID 37510283, 2023). "In contrast, mutations in SRSF2 are highly enriched in the MDS/myeloproliferative syndrome chronic myelomonocytic leukemia (CMML)." (PMID 27151974, 2016). "Notably, SF3B1 mutations are associated with MDS with ringed sideroblasts (MDS-RS), while SRSF2 mutations are linked to chronic myelomonocytic leukemia (CMML)." (PMID 39941875, 2025). "SRSF2 mutations are observed in approximately 5% to 15% of all MDS cases, but their prevalence is higher in chronic myelomonocytic leukemia (CMML)." (PMID 39584923, 2024). "SF3B1 mutations are strongly associated with ring sideroblasts, and SRSF2 mutations are detected in MDS and about half of cases of chronic myelomonocytic leukemia (CMML)." (PMID 37610626, 2023). "Here, a JAK2, an SRSF2, and an ASXL1 variant were detected in a patient with chronic myelomonocytic leukemia." (PMID 35884491, 2022). "Finally, for comparison, in the analysed articles, around 33% of chronic myelomonocytic leukemia (CMML) patients harbored SRSF2 mutations; 8% U2AF1 mutations, 9% ZRSR2 mutations and 5%, SF3B1 mutations." (PMID 32784800, 2020). "SRSF2 mutations appear to play an important role in pathogenesis of MMOS, particularly in chronic myelomonocytic leukemia." (PMID 30275952, 2018). "Occurrence of mutations of SRSF2 varied between 4.3% and 15% in MDS patients and were more frequent in chronic myelomonocytic leukemia (CMML) (29%-46%)." (PMID 28953917, 2017). "SRSF2 mutations are common in AML, MDS, and chronic myelomonocytic leukemia (CMML)." (PMID 40973767, 2025). "SRSF2 mutation (~50%) is one of the most frequent mutations in chronic myelomonocytic leukemia, but it has not been reported to be associated with prognosis." (PMID 38714876, 2024).
chronic myelomonocytic leukemia (continued). "Indeed, SRSF2 mutations are found in 14% of MDS patients and up to 47% of patients with another form of leukemia, chronic myelomonocytic leukemia (CMML)." (PMID 33921778, 2021). "Mutations involving epigenetic regulators (TET2~60% and ASXL1~40%) and splicing components (SRSF2~50%) are frequent in chronic myelomonocytic leukemia (CMML)." (PMID 26771811, 2016).
myelofibrosis (22 papers, 2018 to 2025). A partial or complete replacement of the bone marrow stroma by fibrous tissue. "In more details, NFE2, SRSF2 and EZH2 were associated with secondary myelofibrosis, while SRSF2 and IDH1/2 were associated with AML/MDS transformations." (PMID 40533498, 2025). "Considering the non-driver MPN somatic mutations in the CECs, ASXL1, TET2 and SRSF2 genes were among the most frequently shared mutations and are also known to be the most frequently mutated genes in Myelofibrosis." (PMID 34685741, 2021). "ASXL1, EZH2, and SRSF2 mutations were associated with poor prognosis in primary myelofibrosis (PMF), and the patients could easily transform to s‐AML." (PMID 36799265, 2023). "Mutations of two such factors in SRSF2 and U2AF1 have been identified as high molecular risk mutations in myelofibrosis as both are associated with lower median overall survival compared with wildtype." (PMID 37760623, 2023). "SRSF2 mutations are found in association with JAK2V617F in myeloproliferative neoplasms (MPN), most frequently in myelofibrosis (MF)." (PMID 38012156, 2023). "SRSF2, ASXL1 and U2AF1 mutations predict inferior survival in primary myelofibrosis, independently of other risk factors." (PMID 35740649, 2022). "The patient who progressed to myelofibrosis harbored SRSF2, TET2, and MPL mutations at CMML diagnosis and acquired a JAK2 mutation at the time of myelofibrosis transformation." (PMID 36077644, 2022). "Serine and arginine-rich splicing factor 2 (SRSF2) is multifaceted but appears to be an essential component of pre-mRNA alternating splicing machinery, mutations of which have been identified in approximately 6–17% of patients with myelofibrosis." (PMID 37760623, 2023). "Furthermore, mutations in both SRSF2 and U2AF1 correlated with transformation from PV and ET to myelofibrosis and development of other hematological malignancies." (PMID 37637067, 2023). "The multivariate analysis of all parameters under study clearly showed that the presence of so-called high risk mutations in ASXL1, EZH2, IDH1/2, or SRSF2 is not able to predict progression to myelofibrosis (p = 0.99)." (PMID 33541399, 2021). "Results from our studies suggest that SRSF2 mutant inhibits erythropoiesis but does not promote the development of myelofibrosis in mice expressing Jak2V617F." (PMID 38012156, 2023).
Myelodysplasia (16 papers, 2016 to 2025). Clonal hematopoietic stem cell disorders characterized by dysplasia (ineffective production) in one or more hematopoietic cell lineages, leading to anemia and cytopenia. "The presence of mutations in at least one gene associated with myelodysplasia (i.e., SRSF2, SF3B1, U2AF1, ZRSR2, ASXL1, EZH2, BCOR, or STAG2) was significantly more frequent in older patients." (PMID 35805006, 2022). "Direct association of SRSF2 in development of myelodysplasia was demonstrated in SRSF2-P95H mutant mice." (PMID 30275952, 2018). "In particular, the adverse-risk group has been expanded to include seven additional mutations: BCOR, EZH2, SF3B1, SRSF2, STAG2, U2AF1, and ZRSR2—together with ASXL1 and RUNX1 (already included in ELN 2017)—forming the “myelodysplasia-related” (MR) gene group." (PMID 41464583, 2025). "Males had a higher frequency of mutations in genes of the spliceosome complex (SF3B1, SRSF2, U2AF1 or ZRSR2) (19.1% vs. 5.7% in females; P = 0.002) and the nine myelodysplasia-related genes (31.6% vs. 17.9% in females; P = 0.015)." (PMID 38890297, 2024). "In addition, a second molecular context was evident: CSF3Rmut patients frequently harbored mutations typical of AML with myelodysplasia‐related changes, such as those in ASXL1 and SRSF2." (PMID 41423432, 2025). "Seventy-nine patients, or 45% of all re-classified patients, were moved from ELN-2017 favorable (n = 11) or intermediate (n = 68) to ELN-2022 adverse risk based on the inclusion of additional myelodysplasia-related (MR) mutations (BCOR, EZH2, SF3B1, SRSF2, STAG2, U2AF1, ZRSR2) as poor-risk markers." (PMID 37041198, 2023).
hepatocellular carcinoma (15 papers, 2015 to 2025). A malignant tumor that arises from hepatocytes. "For example, frequent upregulation of mutation-free SRSF2 is a driver in the development of Hepatocellular Carcinoma (HCC)." (PMID 30246013, 2018). "The SRSF2 gene, encoding another splicing machinerycomponent, could be used as a reliable prognostic factor inpatients with hepatocellular carcinoma." (PMID 35342858, 2022). "In tumor diseases, SRSF2 generally appears to be involved in the process of malignant transformation, e.g., in hepatocellular carcinoma." (PMID 41228255, 2025). "Overexpression of SRSF2 has been observed in HCC and knockdown of SRSF2 in human hepatoma cells prevents tumor growth." (PMID 33716968, 2021). "Here, we observe that hepatocyte-specific deletion of Srsf2 trigger development of hepatocellular carcinoma (HCC) in mice, which also involves inflammation and fibrosis." (PMID 32372053, 2020). "SRSF2 protein is highly expressed in hepatocellular carcinoma and predicts a poor prognosis of patients." (PMID 32653017, 2020). "For example, the splicing factor Serine and Arginine Rich Splicing Factor 2 (SRSF2) is upregulated frequently in human hepatocellular carcinoma (HCC), resulting in poor prognosis in patients." (PMID 31857793, 2019). "Our previous studies have shown that miR-193a-3p is involved in multi-drug resistance in both hepatocellular carcinoma and bladder cancer via the repression of different target genes, including SRSF2, PLAU, HIC2 and LOXL4." (PMID 27056900, 2016). "The DNA methylation-regulated miR-193a-3p confers 5-FU resistance to hepatocellular carcinoma (HCC) by repressing SRSF2 expression." (PMID 25991669, 2015). "In addition, SRSF2 increases the proliferation and tumorigenic potential of hepatoma cells by specifically controlling cancer-related splicing events." (PMID 39202384, 2024). "In a study aimed at understanding the resistance of hepatocellular carcinoma to 5-fluorouracil (5-FU), the stability of SRSF2 mRNA, the splicing regulator of caspase 2, which contributes to tumor apoptosis in response to 5-FU, was found to be decreased by DNA methylation-regulated miR-193a-3p34." (PMID 33994855, 2021). "SRSF2 is upregulated in hepatocellular carcinoma (HCC), with its expression being positively correlated with tumor grade and negatively correlated with patient survival time." (PMID 31162605, 2019). "In hepatocellular carcinoma (HCC) cells, miR-193a-3p contributes to the 5-FU resistance regulated by the DNA methylation in particular via repressing SRSF2 expression." (PMID 28073349, 2017).
anemia (12 papers, 2015 to 2026). A reduction in the number of red blood cells, the amount of hemoglobin, and/or the volume of packed red blood cells. "In both cohorts, the proportion of patients with anemia with Hb < 10 g/dl was significantly lower in SRSF2-mutated patients." (PMID 40549056, 2025). "Regarding the phenotype of CMML patients, however, there was an unexpected and consistent finding in both cohorts: in patients with an SRSF2 mutation, the proportion of patients with anemia with Hb < 10 g/dL was lower than among wildtype patients." (PMID 40549056, 2025). "In addition, mutations in U2AF1 were associated with anemia and thrombocytopenia, and SRSF2 with anemia." (PMID 32781570, 2020). "Logistic regression analysis identified IDH1, ASXL1 and SRSF2 mutations, very high-risk karyotype, age > 70 years, male sex, circulating blasts ≥ 3%, presence of moderate or severe anemia and constitutional symptoms, as predictors of LT in the first 5 years of diagnosis." (PMID 30683837, 2019). "In contrast, female sex, constitutional symptoms, anemia, peripheral blood blasts, and ASXL1 and SRSF2 mutations were correlated with inferior PFS." (PMID 36139644, 2022). "Time-to-event Cox analysis confirmed LT prediction for IDH1 mutation (HR 4.3), circulating blasts ≥ 3% (HR 3.3), SRSF2 mutation (HR 3.0), age > 70 years (HR 2.1), ASXL1 mutation (HR 2.0) and presence of moderate or severe anemia (HR 1.9)." (PMID 30683837, 2019). "There was no impact of other laboratory (anemia, thrombocytopenia, serum tryptase) or genetic markers (mutations in SRSF2, ASXL1 or RUNX1) on OS." (PMID 37012462, 2023). "A parallel time-to-event Cox analysis confirmed inferior LFS in patients with IDH1 mutation (HR 4.3), SRSF2 mutation (HR 3.0), ASXL1 mutation (HR 2.0), circulating blasts ≥ 3% (HR 3.3), age > 70 years (HR 2.1), and presence of sex-adjusted moderate or severe anemia (HR 1.9)." (PMID 30683837, 2019).
breast carcinoma (12 papers, 2016 to 2025). "Mutations in some RNA splicing factors, such as SF3B1, SRSF2, and U2AF1, have been found to be involved in the pathogenesis of cancers, such as lung cancer, breast cancer, and pancreatic cancers." (PMID 36371223, 2022). "In our previous study, we demonstrated that Pnn regulates the expression level of SRSF1 and SRSF2 in a breast cancer cell line, MCF-7 (Michigan Cancer Foundation-7), and indicated an SRSF1-dependent Pnn deficiency-induced cellular apoptosis." (PMID 35326115, 2022). "The lncRNA NRON can regulate osteoclastogenesis during orthodontic bone resorption, reduce atrial fibrosis by promoting NFATc3 phosphorylation, inhibit breast cancer development via regulating miR-302b/SRSF2 axis." (PMID 34861891, 2021). "Similarly, SRSF2 has been demonstrated to influence the malignant growth of human breast cancer by controlling the alternative splicing of PLOD2." (PMID 40129567, 2025). "Additionally, among splicing regulators frequently altered in breast cancers (in >5% of tumors), we found different members of SR protein family (such as SRSF1, SRSF2, SRSF3, SRSF4, SRSF6, SRSF9, SRSF10, SRSF11) with at least one predicted binding motif in the CD44 v10 region." (PMID 33143085, 2020). "To find out whether other RBPs regulate translation initiation of specific mRNAs during tumor progression, we first analysed by immunohistochemistry (IHC) the expression of several RBPs (hnRNP A1, hnRNP H, RBM9/FOX2, SRSF1/ASF/SF2, SRSF2/SC35, SRSF3/SRp20, SRSF7/9G8) in breast cancers." (PMID 26930004, 2016).
Thrombocytopenia (10 papers, 2019 to 2025). A reduction in the number of circulating thrombocytes. "The proportion of patients with thrombocytopenia < 100 G/L was significantly higher in SRSF2-mutated patients in the ABCMML cohort and the difference was of borderline significance in the cBioPortal cohort." (PMID 40549056, 2025). "Spliceosome mutations (SF3B1, SRSF2, and U2AF1) were enriched in individuals with thrombocytopenia compared with their matched controls (3.4% vs 1.1%; P = 0.007)." (PMID 36698617, 2023). "Although the prevalence of CH was not increased in thrombocytopenia cases compared with their controls (37.9% vs 39.3%; P = 0.639), mutations in spliceosome genes (SF3B1, SRSF2, U2AF1) were significantly enriched in thrombocytopenia cases (P = 0.007)." (PMID 36698617, 2023). "In the pre-PMF group, we found that thrombocytopenia, ASXL1, MPL, U2AF1, SETBP1, and SRSF2 mutations were associated with inferior overall survival." (PMID 36139644, 2022).